TNF (tumor necrosis factor)
Diseases named in the same sentence as TNF in open-access papers (continued):
Sharing a sentence is not in itself a finding about the gene and the disease.
periodontitis (continued). "Ultimately, these findings suggest that reduced levels of TNF-α and ESM-1 in periodontitis patients following NSPT may be associated with ESM-1 and periodontal inflammation." (PMID 40426985, 2025). "To verify whether the observed synergistic activation of the COX-2-PGE2 axis is specific for TNF, we analyzed the effect of several cytokines that are involved in periodontitis pathogenesis, including IL-1β, IL-1α, and interferon-α (IFNα)." (PMID 40178270, 2025). "In periodontitis, TNF-α levels are increased in gingival crevicular fluid, saliva and serum." (PMID 41153647, 2025). "The hypothesis was that ESM-1, VEGF-A, and TNF-α values would be higher in the periodontitis group than in the control group and would decrease after NSPT." (PMID 40426985, 2025). "The inflammatory microenvironment in periodontitis is characterized by elevated levels of cytokines, including interleukin-1β (IL-1β), tumor necrosis factor-alpha (TNF-α), and interferon-gamma (IFN-γ), which contribute to the breakdown of the extracellular matrix and alveolar bone loss." (PMID 40136681, 2025). "Although anti-TNF-α therapy has been proven beneficial for the treatment of periodontitis, TNF-α monoclonal antibody therapy may lead to autoimmune and skin adverse reactions." (PMID 40083664, 2025). "Similarly, in periodontitis, TNF is involved in regulating inflammatory responses and tissue destruction, becoming a potential treatment target." (PMID 40002889, 2025). "Chronic infections, including periodontitis, might increase circulating cytokines and factors, such as C-reactive protein, interleukin-1 beta, interleukin-6, tumor necrosis factor-alpha, and prostaglandin-E2." (PMID 39229981, 2025). "Ordinal regression analyses revealed significant association between higher salivary TNF-α and TMAO levels and higher odds to present periodontitis in an age-adjusted model (OR: 1.490; 95% CI: 1.021, 2.174; p = 0.039 for TNF-α and OR: 1.094; 95% CI: 1.003, 1.193; p = 0.044 for TMAO)." (PMID 40131489, 2025). "Local inflammatory responses in periodontitis are characterized by the release of cytokines (IL-1β, IL-6, TNF- α), prostaglandins, and matrix metalloproteinases (MMPs) from resident and infiltrating immune cells, leading to tissue destruction and alveolar bone resorption." (PMID 40941475, 2025). "Furthermore, ELISA analysis of periodontitis-related markers in the blood showed that W. cibaria CMU exhibited significant preventive ability to induce periodontitis in TNF-α, IL-6, MMP-1, and MMP-9 categories." (PMID 40007939, 2025). "This synergistic interplay among IL-6, IL-1β, and TNF-α drives extracellular matrix degradation, osteoclastogenesis, and progressive alveolar bone resorption, thereby contributing to the irreversible tissue breakdown characteristic of advanced periodontitis." (PMID 41007333, 2025). "Additionally, the continuous presence of IL-17 induces various inflammatory mediators in endothelial cells, epithelial cells, and fibroblasts, such as IL-1β, TNF-α, and IL-6, which contribute to the activation of osteoclasts in periodontitis." (PMID 40248692, 2025). "The pro-inflammatory cytokine TNF-α (and IL-12) plays a key role in mediating inflammatory responses that promote protective adaptive responses (Th1 and Th17) against pathobionts, thus inhibiting the progression of periodontitis." (PMID 41157245, 2025). "The pathways, such as IL-17 signaling and cytokine–cytokine receptor interactions, underline the important role of proinflammatory cytokines like IL-17, TNF-α, and IL-6 in driving neutrophil recruitment and amplifying the inflammatory response during periodontitis." (PMID 40076622, 2025). "Additionally, critical inflammatory mediators associated with periodontitis, such as iNOS, NLRP3, TNF‐α, and IL‐1β, were significantly modulated." (PMID 41020683, 2025). "A recent scoping review suggests that periodontitis and COVID-19 may independently raise serum levels of IL-1β, IL-6, and TNF-α in the same individual." (PMID 41463036, 2025).
periodontitis (continued). "Conversely, experimental data indicate that periodontitis may aggravate UC by inducing intestinal dysbiosis and promoting pro-inflammatory cytokine secretion, including TNF-α and IL-6 in mice." (PMID 41007498, 2025). "Periodontitis, characterized by chronic bacterial infection and subsequent host inflammatory response, triggers the release of pro-inflammatory cytokines including interleukin-1β (IL-1β), interleukin-6, and tumor necrosis factor-α (TNF-α)." (PMID 41153725, 2025). "In patients with periodontitis and hyperlipidemia, intensive periodontal treatment reduced the serum triglyceride and proinflammatory cytokine levels, that is, tumor necrosis factor-alpha (TNF-α), interleukin (IL)-1β (IL-1β), and IL-6." (PMID 40552326, 2025). "Notably, preclinical research has identified CCL2 as a key chemokine that is significantly upregulated in periodontitis, promoting inflammation and upregulating pro-inflammatory cytokines such as TNFα and IL1β." (PMID 40565042, 2025). "In a controlled trial performed in patients with RA and chronic periodontitis (CP) (RA+CP group), CP and healthy subjects (control), TNF-α levels in crevicular fluid only showed a 1.47-fold reduction after 6 weeks of receiving periodontal therapy in patients with RA+CP, but not in patients with RA." (PMID 40430061, 2025). "Likewise, chemical blockade with reduced signalling in sympathetic nerves enhances TNF-α responses to LPS stimulation and inhibits experimental periodontitis." (PMID 41157245, 2025). "However, in the local periodontitis microenvironment, inflammatory factors, especially TNF-α, tend to inhibit the osteogenic differentiation of PDLSCs." (PMID 39763707, 2025). "Following 4 weeks of therapy, TNF-α correlations intensified markedly with leptin (ρ = 0.671, P < 0.01), resistin (ρ = 0.619, P < 0.01), and periodontal indices (gingival bleeding index: ρ = 0.245; periodontitis grading: ρ = 0.331; P < 0.01)." (PMID 41244040, 2025). "System inflammation due to periodontitis results in elevated TNF-α, CRP AND IL-6 in women with GDM." (PMID 41394354, 2025). "Among them, cytokines such as TNF-α, IL-1β, and IL-6 are highly expressed in patients with periodontitis and promote bone resorption by directly or indirectly supporting not only inflammation but also soft tissue degradation, lymphocyte promotion, and osteoclast formation." (PMID 40733170, 2025). "This suggests that CO could mitigate the destructive effects of IL-6 and TNF-α, providing a novel approach to controlling inflammation in periodontitis." (PMID 40085302, 2025). "Systemic inflammatory mediators, including tumor necrosis factor-alpha (TNF-α) and interleukins, induced by periodontitis, may exacerbate RA by influencing systemic inflammation and joint involvement." (PMID 39987090, 2025). "Among them, the periodontitis-associated genus Rodentibater was positively correlated with TNF-α but inversely associated with PINP, further indicating that Rodentibater may be involved in inflammation and bone metabolism during periodontitis." (PMID 41154794, 2025). "The same could be true for smokers, in particular smokers with periodontitis demonstrate elevated TNF-α plasma levels." (PMID 38627806, 2024). "Based on the data evidenced in the group non-diabetic, in which the circulating IL-10 levels were positively correlated with IL-6 and IFN-γ, at baseline, as well as with TNF-α after the treatment ends, we can suggest that a regulatory status was maintained even with the presence of periodontitis." (PMID 39253540, 2024). "In experimental periodontitis, increased local and systemic TNF levels were reported." (PMID 39253090, 2024). "The presence of LPS during periodontitis induces the production of pro-osteoclastogenetic cytokines such as TNF-α, IL-1, IL-6 by osteoblasts and periodontal ligament fibroblasts, T cells, and B cells, leading to the production RANKL, which has a pivotal function in osteoclast differentiation." (PMID 39456522, 2024).
periodontitis (continued). "As periodontitis is both a local and a systemic condition, we determined the effect of Pg-inoculation on the induction of systemic inflammation by assessing the levels of proinflammatory cytokines such as IL-1β, TNF-α, IL-6, GM-CSF, VEGF, IL-17, and KC." (PMID 38892314, 2024). "A central role seems to be played by two cytokines in periodontitis: TNF-α and IL-1β." (PMID 38792574, 2024). "Previous research data has demonstrated that periodontitis has been linked with increased systemic levels of cytokines, such as interleukin-1α,1β, interleukin-6 (IL-6), C-reactive protein (CRP), TNF tumor necrosis factor-α and interferon-γ in serum or plasma of periodontal compromised individuals." (PMID 39413077, 2024). "However, in periodontitis, pro-inflammatory cytokines, such as interleukin-1beta and tumor necrosis factor-alpha, can promote the destruction of the periodontal tissues." (PMID 38361577, 2024). "Additionally, even though IL-17, IL-1β and TNF were proven to be relevant in mouse models, it is important to question their relevance in the C5-periodontitis axis among humans." (PMID 39439802, 2024). "Moreover, we also observed that pro-inflammatory cytokines TNF-α and IL-6 had higher gene expression in the periodontitis group." (PMID 38319542, 2024). "Meanwhile, in rats with glucocorticoid-induced osteoporosis submitted to periodontitis, ATV at 27 mg/kg decreased bone loss, reduced myeloperoxidase (MPO), TNF-α, IL-1β, IL-6, and IL-8, and increased IL-10, glutathione (GSH), superoxide dismutase (SOD), and catalase (CAT) levels." (PMID 39476053, 2024). "Consistently, another report showed that TNF blockade reduces periodontitis activity." (PMID 39253090, 2024). "Moreover, both periodontitis and OA are mediated by proinflammatory cytokines such as interleukin (IL)-1β and tumor necrosis factor (TNF)-α64." (PMID 38383594, 2024). "In chronic periodontitis, IL-1 as well as the pro-inflammatory cytokine TNF have been suggested to control the spread of an inflammatory front to deeper areas in the connective tissue where they drive loss of connective tissue attachment, osteoclast activation and subsequent loss of alveolar bone." (PMID 39253090, 2024). "This may reflect the complex pathogenesis of the inflammatory process in periodontitis, which is influenced by several cytokines and chemokines, such as IL-1, TNF-α, and IL-17, and interactions between them." (PMID 39458264, 2024). "No doubt, tissue affected by periodontitis is associated with an imbalance between pro and anti-inflammatory cytokines (IL-17, IL-23, IL-6, IL-8, TNF-α, and interferon-γ) in favor of pro-inflammatory burden." (PMID 39445112, 2024). "Therefore, our results regarding TNF-α expression support TNF-α’s role in the periodontitis–oral cancer connection, which is crucial for understanding the molecular mechanisms that are involved." (PMID 38612423, 2024). "Several inflammatory factors are relevant to the periodontitis, such as TNF-α, IL-1β, and IL-641." (PMID 38698209, 2024). "ET-1 plays an important role in the pathogenesis of periodontitis; previously reported found that exposure to Porphyromonas gingivalis induces ET-1 secretion from endothelial cells and stimulates inflammatory cytokines such as IL-1β and TNF-α." (PMID 38874661, 2024). "Periodontitis induces a chronic inflammatory response in the periodontal tissues, characterized by the release of pro-inflammatory cytokines such as interleukin-1 beta (IL-1β), TNF-α, and IL-6." (PMID 39189252, 2024). "Our data were consistent with a previous report where the activated Piezo1 contrarily triggered M1 macrophage polarization in response to LPS, triggered overproduction of proinflammatory cytokines (e.g. TNF-α and IL-1β) and ultimately contributed to collagen degradation in periodontitis." (PMID 38303078, 2024).
periodontitis (continued). "Additionally, periodontal tissue affected by periodontitis showed an increase in the M1 inflammatory factors TNF-α and IL-1β as well as the M2 inflammatory factor IL-10." (PMID 38347915, 2024). "Macrophages play a key role in both the destructive and reparative phases of periodontal disease, as they differentiate into M1-type during the early stages of periodontitis and secrete high levels of pro-inflammatory cytokines such as IL-1β, IL-6, TNF-α, and IFN-γ." (PMID 38319542, 2024). "In human periodontitis, Tregs can express TNF- α, which might regulate the immunologic process of periodontitis." (PMID 38580668, 2024). "Nevertheless, even though TNF-α may be a sign of periodontitis, its function in thyroid disorders is still unknown." (PMID 39063437, 2024). "Furthermore, previous studies have shown that PL effectively downregulates IL-1β expression in a mouse model of osteoarthritis, as well as inhibits TNF-α and IL-6 levels in a rat model of chronic periodontitis, which aligns with our observations." (PMID 38655086, 2024). "Periodontitis, as a chronic inflammatory disease, triggers the release of pro-inflammatory cytokines such as interleukin-6 (IL-6), interleukin-1β (IL-1β), and tumor necrosis factor-alpha (TNF-α), which not only mediate tissue destruction in the periodontal tissues but also activate the SNS." (PMID 39590320, 2024). "TNF-α is involved in the pathogenesis of both arthritides and periodontitis." (PMID 38256582, 2024). "Therefore, we evaluated the effect of HKT on pro-inflammatory mediators iNOS and COX-2 and the major inflammatory cytokines of periodontitis, IL-6, IL-1β, and TNF-α, in an actual inflammatory situation." (PMID 38790655, 2024). "Indeed, patients with periodontitis display increased levels of IL-6 and TNF-α in serum, saliva and gingival crevicular fluid." (PMID 39274511, 2024). "This study affirmed that quercetin possessed the ability to restore osteo-/angiogenic differentiation capacity as well as inhibit the pro-inflammatory factors’ production including IL-6 and TNF- α in inflammatory PDLSCs, which was beneficial for alveolar bone regeneration in periodontitis." (PMID 38449005, 2024). "In this regard, it has been seen that GMSCs treated with TNF-α release exosomes enriched in CD73, which promote the polarization of macrophages towards an M2 phenotype, which correlates with reduced bone loss in a murine model of periodontitis." (PMID 38396665, 2024). "As the relationship between TNF-α expression and periodontal disease has been well-documented, it may be used as an indicator for treating and responding to periodontitis." (PMID 39548434, 2024). "Chronic periodontitis patients also show elevated TNF-α levels in gingival serum." (PMID 39630805, 2024). "The increasing level of resistin in obese patients and rats with periodontitis might be due to its ability to recruit TNF-α and IL-6." (PMID 38069063, 2023). "Periodontitis, a potential risk factor for CVD, has been suggested to be associated with serum levels of these molecules, adiponectin, and other inflammatory mediators, such as tumor necrosis factor-alpha (TNF-α) and C-reactive protein (CRP) as well." (PMID 37371602, 2023). "Given the disproportionate burden of periodontitis, a growing body of literature investigates the potential efficacy of immunomodulatory treatments, including TNF inhibitors, in periodontal diseases; however, drug development remains hindered by the high cost and failure rates." (PMID 36845132, 2023). "In contrast, the activation of T cells under inflammatory conditions can lead to increased production of RANKL and Tumor Necrosis Factor-α (TNF-α), which promote osteoclast production and bone loss under kinds of inflammatory and autoimmune conditions, such as periodontitis, cancer and osteoporosis." (PMID 37064239, 2023). "In addition, inflammatory factors of periodontitis, such as IL-1β, IL-6, IL-8, and TNF-α also significantly reduced in the Fn+AKK group." (PMID 37460552, 2023).
periodontitis (continued). "In P. gingivalis-associated ligature-induced experimental periodontitis, the adoptive transfer of Breg cells (CD1dhiCD5+) induced a gingival decrease in the production of RANKL, TNF-α, and IL-1β and an increase in the production of IL-10, which inhibited periodontal bone loss." (PMID 37217496, 2023). "The findings of this study are consistent with previous research that has shown TNF-α to be a potent early pro-inflammatory cytokine in destructive periodontitis, and that its activities in the periodontal tissues include degradation of the connective tissues and stimulation of osteoclast formation." (PMID 37232780, 2023). "Periodontitis is a common chronic inflammatory disease that is characterized by disordered glucose metabolism and the cytokines: interleukin-1 (IL-1), interleukin-6 (IL-6), tumor necrosis factor-α (TNF-α), and interleukin-17A (IL-17A)." (PMID 38098816, 2023). "TNF inhibitors are usually prescribed for a specific time period, whereas our study aimed to reveal long-term effect of the blockage of TNFR1 on the risk of periodontitis." (PMID 36845132, 2023). "In addition, TNF‐α and IL‐1β stimulate NO expression, which enhances the progression of periodontitis." (PMID 36894516, 2023). "It was previously reported that IL-11 is underexpressed in periodontitis, while TNF-α is overexpressed, there is a reduction of VEGF in periodontal disease, and these are correlated with the resolution of periodontal inflammation and periodontal tissue healing." (PMID 36826852, 2023). "Furthermore, caspase-1 and TNF-α showed high sensitivity and specificity in the diagnosis of periodontitis, as well as distinguishing periodontitis from periodontal health." (PMID 36794778, 2023). "Also, in a mouse model of hyperlipidemia with periodontitis, GMSCs significantly reduce the serum levels of pro-inflammatory cytokines IL-6 and TNF-α, while increasing the anti-inflammatory cytokine IL-10 and improving periodontal tissue regeneration." (PMID 37626831, 2023). "Ligature-induced periodontitis significantly increased periodontal bone loss in 3 × Tg-AD, which was accompanied by increased total bacterial load and elevated gene expression levels of MCP-1, TNF-α and IL-1β in the gums." (PMID 36915108, 2023). "Similarly, Mohammad found a significant reduction of IL-11β and TNF-α in the group of patients with chronic periodontitis, treated by scaling and root planing and curcumin gel injection, in a comparative clinical study." (PMID 37600299, 2023). "Thus, it is suggested that future research measure the level of TNF-α and caspase-1 relative to the severity of periodontitis." (PMID 36794778, 2023). "TNF-α gained particular attention since this cytokine is known to play a fundamental role in periodontal disease, as it activates osteoclasts that facilitate bone resorption and periodontitis." (PMID 37629193, 2023). "Previous research has highlighted the significant role of TNF-α in the pathogenesis of destructive periodontitis, and our study found that activated Wnt signaling plays a complex and cell-type specific role in TNF-α expression, suggesting a modulating effect on inflammation during periodontitis." (PMID 37232780, 2023). "However, treatment with FK506/EPO effectively suppressed the increase in serum TNF-α, IL-1β, and IL-6 induced by experimental periodontitis." (PMID 38239915, 2023). "Additionally, there was a statistically significant correlation between generalised periodontitis parameters and the presence of TNF-α (p < 0.000)." (PMID 36794778, 2023). "TNF was elevated in patients who had clinical indicators of periodontitis, suggesting that this biomarker may be useful in a panel of salivary biomarkers that could facilitate the screening, diagnosis, and management of periodontal diseases." (PMID 36845132, 2023). "Catechin’s suppressive effect on IL-1β and TNF-α production may provide a beneficial approach for modulating periodontitis." (PMID 37509571, 2023).